MET (MET proto-oncogene, receptor tyrosine kinase)
Diseases named in the same sentence as MET in open-access papers (continued):
Sharing a sentence is not in itself a finding about the gene and the disease.
renal cell carcinoma (continued). "Numerous selective c-Met inhibitors have been developed, such as savolitinib (in clinical trials for renal cell carcinoma), capmatinib and tepotinib (authorized for MET exon 14-altered NSCLC), and crizotinib (initially an ALK/c-Met inhibitor, FDA-approved for NSCLC)." (PMID 41471364, 2025). "Applying our pre‐clinical findings, we then treated two patients (one with a non‐small‐cell lung cancer and one with a renal cell carcinoma) whose tumours harboured these previously uncharacterised MET alterations with cabozantinib, a type II MET TKI, and observed clinical responses." (PMID 40437874, 2025). "The cited authors report that VHL, BAP1, FH, and MET are specific genes that increase the risk of developing renal cell cancer, whereas CHEK2, MUTYH, APC, and STK1 are not typically associated with the development of renal tumours." (PMID 39336594, 2024). "The receptor tyrosine kinase c-MET regulates cell growth and differentiation as well as basic tumor pathobiology like tumor development, tumor angiogenesis, and tumor dissemination for a range of malignancies such as renal cell carcinoma." (PMID 34708249, 2022). "Some studies have shown that exosomal lncRNA ARSR could competitively bind to miR-34 and miR-449 to regulate the expression of AXL, c-MET, and then promoted the drug resistance of renal cell carcinoma." (PMID 32587476, 2020). "MET fusions have been identified in several tumour types including gastric cancer, melanoma, thyroid carcinoma, papillary renal cell carcinoma (RCC), lung adenocarcinoma, hepatocellular carcinoma, glioma, colorectal cancer and sarcoma." (PMID 40437874, 2025). "Cabozantinib is a multi-kinase inhibitor targeting c-MET, VEGFRs, and other RTKs and has demonstrated significant efficacy in cancers such as renal cell carcinoma (RCC)." (PMID 41019287, 2025). "For example, lncARSR promotes sunitinib resistance via competitively binding miR‐34/miR‐449 to facilitate AXL and c‐MET expression in renal cell carcinoma (RCC) cells, and intercellular transfer of lncARSR by exosomes disseminated sunitinib resistance." (PMID 32578911, 2020). "Can it be more effective by targeting both the vascular endothelial growth factor receptor (VEGFR) and MET signaling pathways in sporadic metastatic papillary renal cell carcinoma (RCC)?" (PMID 28974261, 2017). "Risk factors and comorbidities might be associated to renal cell carcinoma, while a small fraction of 2–3% emerges from patients with predisposing cancer syndromes, typically associated to hereditary mutations in VHL, folliculin, fumarate hydratase or MET genes." (PMID 38512353, 2024). "Previous studies have demonstrated that exosomal lncARSR promotes sunitinib-resistant renal cell carcinoma by upregulating the expression of AXL and c-MET in recipient cells." (PMID 36765853, 2023). "Genomic studies identifying the genes for kidney cancer, including the VHL, PBRM1, MET, FLCN, fumarate hydratase, succinate dehydrogenase, TSC1, TSC2, and TFE3 genes are known to play role in renal cell carcinoma development." (PMID 35709632, 2022). "In this study, we used MET-, EGFR-, and HER2-targeted immuno-PET to detect RTK protein levels after targeted therapy in a renal cell carcinoma (RCC) patient–derived xenograft (PDX) model." (PMID 32646879, 2021). "Exosome-transmitted lncARSR functions as a sponge of miR-34/miR-449 to induce c-MET and AXL expression and mediates sunitinib resistance in renal cell carcinoma." (PMID 33154765, 2020). "Exosomal lncRNA activated in RCC with sunitinib resistance (lncARSR) was delivered to renal cell carcinoma to promote sunitinib resistance through sponging miR-34/miR-449, which further enhanced AXL and c-MET expression." (PMID 33072553, 2020). "Furthermore, both MET and AXL are involved in resistance to antiangiogenic agents in renal cell carcinoma; overexpression of these kinases was observed in HCC tumors that developed acquired resistance to sorafenib." (PMID 35062934, 2022).
renal cell carcinoma (continued). "These biomarkers were selected based on biological relevance to renal cell carcinoma, previous reports of prognostic significance, and the target profile of cabozantinib including both cabozantinib receptor targets (VEGFR2, MET, and AXL) and their ligands (VEGF, HGF, and GAS6)." (PMID 34364385, 2021). "The majority of the genes involved in hereditary renal cell carcinoma (RCC) are HRPT2, FH, BHD, MET, VHL, and FH." (PMID 38666938, 2024). "A recent phase III clinical study of cabozantinib—which inhibits AXL in addition to MET and VEGFR—in renal cell carcinoma (RCC) patients progressing after VEGFR inhibitor treatment, supports the hypothesis that AXL inhibition could target resistance to VEGFR inhibition." (PMID 28251492, 2017).
small cell lung carcinoma (76 papers, 2007 to 2025). Small cell lung cancer (SCLC) is a highly aggressive malignant neoplasm, accounting for 10-15% of lung cancer cases, characterized byrapid growth, and early metastasis. "The mechanisms of resistance vary, including secondary EGFR mutations, amplification of MET, and transformation to small cell lung cancer (SCLC)." (PMID 41001033, 2025). "Small cell lung cancer was the first disease to be linked to somatic mutations affecting splicing sites of exon 14 of the MET gene, which codes for the juxtamembrane region." (PMID 36499382, 2022). "MET gene amplification and transformation into small-cell lung cancer are also associated with TKI resistance." (PMID 32298306, 2020). "Clinically, EGFR-positive NSCLC acquires several resistance mechanisms during EGFR-TKI treatment, such as the emergence of a secondary mutation (T790M), MET gene amplification, and transformation to small cell lung cancer." (PMID 30290647, 2018). "In the case of T790M loss, several genetic alterations have been observed, including those related to transformation to small cell lung cancer, MET amplification, ERBB2 amplification/mutation, PIK3CA mutation, KRAS mutations, and oncogenic gene fusion involving RET, FGFR3, and BRAF." (PMID 34831415, 2021). "T790M serial monitoring could be less useful for the subset of patients who develop additional mechanism of resistance to third-generation TKIs, including other novel mutations such as C797S, small cell lung cancer transformation, or MET amplification." (PMID 29930751, 2018). "For example, targeting c-MET has been investigated as a potential treatment strategy for small cell lung cancer." (PMID 40520181, 2025). "The PG acquired resistance to EGFR-TKIs through the MET amplification (27, 50%) and small cell lung cancer transformation (16, 30%) and 18% of them reported multiple resistance mechanisms." (PMID 38402169, 2024). "Resistance mechanisms, such as the bypass signaling pathway, PTEN loss, MET amplification, MYC amplification, and small cell lung carcinoma transformation, have been described in previous reports." (PMID 38012343, 2023). "Molecular mechanisms of acquired resistance to EGFR-TKIs have been well elucidated, including secondary T790M mutation (50–60%), MET amplification (5–22%), HER2 amplification (~ 12%) and transformation to small cell lung cancer (SCLC) (3–10%)." (PMID 37161388, 2023). "EGFR pathway-independent mechanisms include MET amplification, HER2 amplification, FGFR1 amplification, BRAF mutation, KRAS mutation, and histologic transformation to small cell lung cancer." (PMID 30875928, 2019). "Preclinical findings also showed that the aberrant c-MET/HGF pathway plays an important role in cytotoxic chemotherapy (CC) resistance in small-cell lung cancer (SCLC)." (PMID 29069748, 2017). "As well as this mechanism, c-MET amplification (5– 10%), HER2 amplification (12%), PIK3CA mutations (5%), BRAF mutations (1%), small-cell lung cancer histological transformation (3–14%) and so on are also associated with acquired resistance to EGFR-TKIs." (PMID 27409677, 2016). "Tumor cells acquire resistance to these compounds through multiple mechanisms, including a second-site mutation (T790M) in EGFR, amplification of MET or ERBB2, and conversion to a small cell lung cancer phenotype." (PMID 26047463, 2015). "c-MET overexpression has been observed in 67% of adenocarcinomas, 57% of large cell carcinomas, 57% of squamous cell carcinomas, and 25% of small cell lung cancers." (PMID 22363766, 2012). "The authors categorize resistance into EGFR-dependent mechanisms (e.g., secondary mutations like T790M and C797S), bypass pathway activation (e.g., MET or HER2 amplification, KRAS mutations, and BRAF mutations), and histologic transformation (e.g., small-cell lung cancer)." (PMID 40416863, 2025). "A search of clinicaltrials.gov does not reveal any ongoing trials of MET Exon 14 skipping mutation inhibitors in the small cell lung cancer space." (PMID 34425853, 2021).
small cell lung carcinoma (continued). "Also, different subtypes also had their own specific variants, such as MET in adenocarcinoma, FGFR1 and FGFR3 in squamous cell carcinoma and MYC in small cell lung cancer." (PMID 31616594, 2019). "Several mechanisms leading to acquired resistance have been demonstrated, including EGFR T790M mutation, MET amplification, PIK3CA mutation, AXL activation, small cell lung cancer (SCLC) transformation, or acquiring an epithelial-to-mesenchymal transition (EMT) phenotype." (PMID 29717264, 2018). "This is associated with second-site mutations in the EGFR kinase gene (e.g., T790M), amplification of alternative kinases (e.g., mesenchymal-epithelial transition factor, MET), histologic transformation to small cell lung cancer (SCLC), and epithelial to mesenchymal transition." (PMID 25699082, 2015). "c-MET mutations have been observed in both NSCLC and small cell lung cancer." (PMID 22363766, 2012). "In addition to the drug resistance conferred by the C797S mutation in EGFR, amplification of the MET gene as a bypass pathway, alteration in RAS-RAF-MAPK pathway, ROS1 fusion gene, PIK3CA mutation, and transformation to small cell lung cancer are other mechanisms that impart drug resistance." (PMID 34831415, 2021). "As far as we know, MET Exon 14 skipping mutation has not been found in small cell lung cancer." (PMID 34425853, 2021). "Small cell lung carcinoma is characterized by high invasive and metastatic capacity, a typical feature of MET-activated tumour models and previous studies suggest a role for MET in SCLC." (PMID 21847116, 2011). "Earlier research has demonstrated that in small-cell lung cancer, the activation of Chk1 through the upregulation of AXL and MET pathways is a significant mechanism of resistance to AZD-1775." (PMID 37296592, 2023). "For what concerns Small-Cell Lung Cancer (SCLC), the activation of HGF/c-MET pathway leads to increased tumor growth and cell survival." (PMID 35069735, 2022). "Other known biological resistance mechanisms include MET amplification, EGFR amplification, PIK3CA amplification, HER2 amplification, and histologic transformation to small cell lung cancer." (PMID 30875928, 2019). "As an example, in small cell lung cancer (SCLC), activation of MET with HGF leads to phosphorylation/activation of several pathways involving cell proliferation/survival (ERK1/2, AKT), cell cycle (RB), and cytoskeletal proteins (paxillin, FAK)." (PMID 19955662, 2009). "Alternative signaling pathways, such as MET amplification, may also be activated, as are other mechanisms such as HER2 amplification, PIK3CA, KRAS, BRAF, and small cell lung cancer transformation." (PMID 39231972, 2024). "In tyrosine kinase inhibitors (TKIs)-resistant small cell lung cancer cell lines, AMF-26 induced downregulation of MET, which is also known as hepatocyte growth factor receptor, suggesting that anticancer mechanism of AMF-26 was different from that of known EGFR-TKIs." (PMID 37046746, 2023). "Further, patients with never/ever smoking history who present with small-cell lung cancer have a different mutation profile compared with smokers, including a high frequency of EGFR, MET, and SMAD4 mutations." (PMID 31058075, 2019).
bladder cancer (72 papers, 2005 to 2025). "Herein, for the first time we revealed that the process of acquired resistance to the novel FGFR inhibitor was associated with increased expression of MET in lung, gastric, and bladder cancer cells." (PMID 33898310, 2021). "However, the mechanisms underlying HGF/c-MET-mediated invasion in bladder cancer remain poorly defined." (PMID 33823905, 2021). "However, phosphorylated MET was significantly associated with tumor aggressiveness and prognosis in patients with bladder cancer patients." (PMID 25521854, 2014). "In this study, we analyzed the therapeutic effect of HAI-1 and HAI-2 on bladder cancer cells through the inhibition of MET phosphorylation." (PMID 40299447, 2025). "Tumor-infiltrating neutrophils secrete HGF, which activates MET signaling in bladder cancer cells, promoting proliferation, invasion, and EMT." (PMID 41315241, 2025). "In bladder cancer, a correlation between the phosphorylation of MET and a poor prognosis was also reported." (PMID 40299443, 2025). "In bladder cancer, for example, loss of methylation at a LINE-1 promoter has been shown to initiate an alternative transcript of the MET oncogene, thereby promoting tumorigenesis." (PMID 40558829, 2025). "Aberrant hepatic growth factor (HGF)/c-MET upregulation and activation is frequently observed in bladder cancer correlating with cancer progression and invasion." (PMID 33823905, 2021). "First, co-culture of CD4+ T cells promoted the proliferation and invasion of bladder cancer cells and considerably increased the expression of not only MET oncogene and c-MET but also ERβ in bladder cancer cells." (PMID 33796076, 2021). "The regulatory role of CCNA2 in the MET-mediated cell-cycle pathway is reportedly blocked by miR-381-3p, which promotes the proliferation and metastasis of bladder cancer cells." (PMID 34093807, 2021). "For instance, one panel of methylation biomarkers for bladder cancer detection includes L1-MET, the L1 element next to the MET oncogene." (PMID 33322422, 2020). "However, the mechanisms underlying HGF/c-MET-mediated invasion in bladder cancer remains unknown." (PMID 31554791, 2019). "In summary our findings suggest that TβR activation is a critical factor in c-MET induced bladder cancer invasion and further studies into the potential use of TβR and MAPK inhibitors is warranted." (PMID 31554791, 2019). "Similar oncogene activation by L1-ASP has been reported in other cancer types, such as MET activation in bladder cancer." (PMID 31061680, 2019). "Aberrant HGF/c-MET upregulation and activation is frequently observed in bladder cancer correlating with cancer progression and invasion." (PMID 31554791, 2019). "In bladder cancer, although phosphorylation of MET (Y1349) was reported to correlate with high T stage, metastasis and poor prognosis, expression of matriptase has not been evaluated." (PMID 30469509, 2018). "This is the first study to analyze the expression of matriptase and HAI-1, and to examine correlation with the phosphorylation of MET in bladder cancer specimens by immunohistochemistry." (PMID 30469509, 2018). "In bladder cancer, phosphorylation of MET is reported to correlate with the progression and poor prognosis." (PMID 30469509, 2018). "Previous studies have shown that c-MET is overexpressed in cases of aggressive bladder cancer (BCa)." (PMID 26225770, 2015). "Strong MET expression has been demonstrated in an invasive phenotype of bladder cancer, although varying levels of MET immunostaining are consistently detected in UC of the bladder." (PMID 25521854, 2014). "Noteworthy, DNA hypomethylation of a specific LINE-1 element within the MET oncogene was recently shown to enable expression of a chimeric L1-MET transcript starting from the ASP in bladder cancers." (PMID 24133654, 2013).
bladder cancer (continued). "This suggested that ligand-dependent activation of MET was critical in bladder cancer, and the inhibition of HGF activation by HAI-1 might have the potential to regulate the progression of cancer." (PMID 40299447, 2025). "Findings from cell culture and animal models showed that ERβ signaling is induced by infiltrating T cells and consequently increased MET expression directly by binding to MET gene promoter or through modulation of interleukin-1 expression in bladder cancer, leading to invasion and metastasis." (PMID 39742369, 2024). "Based on these results we used an orthotopic mouse model of bladder cancer whereby we could analyze the role of c-MET-mediated invasion." (PMID 31554791, 2019). "In a previous study, we reported upregulated MET phosphorylation and decreased expression of HAI-1 in bladder cancer as poor prognostic factors." (PMID 40299447, 2025). "In bladder cancer, CD4+ T cells facilitate tumor invasion through the ERβ/c-MET and ERβ/IL-1/c-MET pathways." (PMID 40303343, 2025). "Another experiment also proved that miR-381-3p blocks the dual regulatory role of CCNA2 (Cyclin-A2) in modulating CDK6 and MET-mediated cell-cycle pathway and EMT progression in bladder cancer." (PMID 36856518, 2023). "Collectively, these observations indicate that HGF/MET signaling triggers a Pyk2-mediated mechanism of resistance to FGFR inhibitor that appears to be common in lung, gastric, and bladder cancer cells." (PMID 33898310, 2021). "Our results demonstrate that the HGF/MET-Pyk2 signaling axis confers resistance to the novel FGFR inhibitor, and this mechanism is common for lung, gastric, and bladder cancer cells." (PMID 33898310, 2021). "To identify the mechanisms through which HGF and its cognate receptor, c-MET, induces EMT in bladder cancer we treated the rat bladder carcinoma cell line NBT-II, with either HGF or EGF and analysed changes in cellular morphology with EMT marker expression." (PMID 31554791, 2019). "Immunohistochemical findings showed reciprocal expression of HAI-1 and phospho-MET, which revealed the importance of HAI-1-induced regulation of MET phosphorylation as a major synergic role in the progression of bladder cancer." (PMID 30469509, 2018). "In this study, we found that expression of RON or MET, or both, is positively associated with aggressive biological indicators and decreased patient survival, which supports the hypothesis that RON-related signalling events play an important role in the progression of bladder cancer." (PMID 15870710, 2005). "In addition, no apparent statistical correlation was also observed between the expression of HGF, MET, ST14, HPN, and HGFAC and the prognosis of patients with bladder cancer by GEPIA." (PMID 40299447, 2025). "In addition to other EGFR family members, MET can heterodimerise with ERBB3 to induce intracellular signalling and is a known inducer of EMT in bladder cancer cells." (PMID 36385700, 2023). "In bladder cancer, the major source of increased serum HGF levels is likely the tumor itself; several studies have demonstrated the involvement of the HGF/MET pathway in the development of aggressive tumors." (PMID 34997350, 2022). "In addition to MET expression, interaction with the Axl and PDGFR-α pathways contributes to bladder cancer progression." (PMID 25521854, 2014). "As crosstalk between RON and MET was observed in epithelial cancer, we investigated the clinical significance of RON and MET overexpression in human bladder cancer." (PMID 15870710, 2005). "In bladder cancer, miR-381-3p has also been found to regulate the cell cycle of bladder cancer cells, increasing apoptosis rate by targeting negative regulation of CDK6, CCNA2, and MET." (PMID 38818039, 2024).